CXCR4 (C-X-C motif chemokine receptor 4)
Diseases named in the same sentence as CXCR4 in open-access papers (continued):
Sharing a sentence is not in itself a finding about the gene and the disease.
brain tumor (25 papers, 2008 to 2025). "Overexpression of the chemokine-4 receptor (CXCR4) in brain tumors is associated with high cancer cell invasiveness." (PMID 32410920, 2020). "To validate these novel radiolabeled cyclam derivatives for diagnostic CXCR4 imaging efficacy in brain tumors, we established appropriated murine models of intracranial GBM and PCNSL." (PMID 32239371, 2020). "PET studies were performed in mice bearing CXCR4-expressing U87 brain tumors and HT-29 colon tumors." (PMID 34500609, 2021). "The expression of CXCR4 in human brain tumors and the potent anti-xenograft activity of the selective CXCR4 antagonists AMD 3100 and AMD 3465 position CXCR4 among the few validated targets for molecular therapy of malignant brain tumors." (PMID 34575965, 2021). "A future objective, after validating a CXCR4 imaging paradigm, would be to screen brain tumor patients for anti-CXCR4 targeted-radiotherapy." (PMID 32239371, 2020). "Then, we tested 76Br-HZ270-1 in appropriate murine orthotopic models of GBM and PCNSL to validate the imaging efficacy of this radiolabeled cyclam derivative two brain tumor models that express high levels of CXCR4 protein." (PMID 32239371, 2020). "Subsequent investigations revealed that fingolimod decreased recruitment of macrophages to the brain tumor microenvironment, as well as pushed them toward a proinflammatory (M1) phenotype via C-X-C Motif Chemokine Receptor 4 (CXCR4) internalization." (PMID 32977496, 2020). "Lastly, we tested the effects of radiation on CXCR4 knock down GL26-Cit cells in an orthotopic brain tumor model." (PMID 27863376, 2016). "CXCL12 is also upregulated in the brain tumor microvasculature, and blocking the CXCR4 axis with antagonists AMD3100 and AMD3465 resulted in significant anti-tumor effects in animal models." (PMID 25238146, 2014). "CXCR4 expression is elevated in many brain tumor types, including GBM, where increased expression is associated with a worse prognosis." (PMID 25238146, 2014). "The significance of the expression and function of the CXCL12/CXCR4 axis in brain tumors has been intensely investigated in adult and children GBM, astrocytoma, medulloblastoma, oligodendroglioma, and oligodendroastrocytoma." (PMID 24904289, 2014). "Together, these studies underscore the potential complexity of CXCL12 effects on brain tumor growth and the possibility for multiple mechanisms of CXCR4 antagonist action." (PMID 22427929, 2012). "The ultimate criterion is to test that expression scale of CXCR4 correlates the stem cell capacity of targeting brain tumors in vivo." (PMID 18498656, 2008). "Gene profiling revealed that BV2 cells expressed higher levels of both M2‐associated genes (Maf, Selenop, P2ry14, Mrc1, Ctsc, and Cxcr4) and M1‐associated genes (Il7r, Atf3, and Gadd45g) compared to RAW264.7 cells, suggesting its multifaceted role in interaction with brain tumors." (PMID 40747560, 2025). "Moreover, both individual CXCL12 receptors, i.e., CXCR4 and CXCR7, are implicated in brain tumor growth in vitro and in vivo." (PMID 36568151, 2022). "However, imaging CXCR4 expression in brain tumors with 68Ga-pentixafor and 68Ga-NOTA-NFB has been more limited." (PMID 32239371, 2020). "However, imaging CXCR4 expression in brain tumors with 68Ga-pentixafor and 68Ga-NOTA-NFB has been less successful." (PMID 32239371, 2020). "The potential to develop radiolabeled Plerixafor analogues for imaging CXCR4 expression in brain tumors exists and could be used for selecting patient targeted treatment and for monitoring treatment efficacy." (PMID 32239371, 2020). "This research aimed to estimate the biokinetic behavior and radiation dosimetry of 99mTc-CXCR4-L in healthy subjects, as well as to correlate the radiotracer uptake by brain tumors in patients, with the histological grade of differentiation and CXCR4 expression evaluated by immunohistochemistry." (PMID 32410920, 2020). "Additionally, brain tumor cell lines, primary tumors, and metastases overexpress CXCR4." (PMID 32260318, 2020).
brain tumor (continued). "If resistance to radiation therapy and chemotherapy are dependent upon localization to the peri-endothelial cell space, then mobilization of brain tumor cells with CXCR4 antagonists could be used in combination with radiation or standard chemotherapy to greater effect." (PMID 22427929, 2012). "It is well-suited for imaging CXCR4 expression in hematological malignancies and SCLC, as well as for imaging and evaluating the treatment of primary brain tumors." (PMID 39431004, 2024). "In combination with radiotherapy, antagonists to CXCL12, CXCR4 and CXCR7 have led to complete brain tumor regression and survival prolongation of tumor-bearing rodents." (PMID 36568151, 2022). "High expression levels of CXCR4 and its ligand, the chemokine stromal cell-derived factor 1-α (SDF1-α = CXCL12), usually indicate a poor prognosis for patients with brain tumors." (PMID 32410920, 2020). "The essential driving force for stem cell migration toward brain tumors is the binding chemokine (e.g., SDF-1) to its chemokine receptor (e.g., CXCR4) that mediates the signal transduction." (PMID 18498656, 2008). "Several reports showed that the treatment with VEGFR inhibitor determined the activation of CXCL12/CXCR4 pathway, increasing circulating CXCL12 levels and CXCR4+ cells and the infiltration of myeloid BMDC in brain tumors and promoting angiogenesis, tumor growth, and metastasis." (PMID 26880981, 2016). "ADSCs are mesenchymal stem cells obtained from adipose tissue with the capacity of homing to brain cancer via stromal cell-derived factor-1α/C-X-C chemokine receptor type 4 (SDF-1α/CXCR4) signaling axis, thus could serve as therapeutic vehicles for targeted brain tumor delivery." (PMID 37111742, 2023). "Besides brain tumors, AMD3465 was also capable of preventing in vivo breast cancer growth and metastasis, while LY2510924, a novel cyclic peptide CXCR4 antagonist, exhibited antitumor activities in various solid tumor and metastatic breast cancer preclinical models." (PMID 34575965, 2021). "Targeting the ligand, CXCL12, rather than its receptor, CXCR4, NOX-A12 is another inhibitor of the axis that is to be tested in brain tumors in combination with radiotherapy." (PMID 30813533, 2019). "CXCR4, a CXCL12 receptor, is expressed on brain tumor cells and high levels of expression have negative prognostic significance." (PMID 22427929, 2012).
oral cancer (25 papers, 2008 to 2025). "To further investigate the role of CXCR4 in tumor-associated vasculature, we utilized the murine oral cancer models." (PMID 41210695, 2025). "We then checked the association between MRE11 and CXCR4 by immunohistochemistry using oral cancer tissue specimens." (PMID 33927349, 2021). "Mutation in the gene of a specific chemokine receptor (CXCR4) has been noted to have an increased likelihood of more advanced oral cancer (stage III and IV by 2.66-fold)." (PMID 24376459, 2013). "Taken together, the association between CXCR4 and mGluR5 is strongly suggested to promote the progression of oral cancer." (PMID 24236200, 2013). "In this study, we examined the expression of CXCR4 associated with the chemotherapeutic agents in oral cancer cells." (PMID 19671192, 2009). "CXCR-4 inhibition causes oral cancer cells to lose their ability to metastasize and proliferate." (PMID 34885003, 2021). "Although CXCR-4 and CD133 have been examined for their expression patterns and prognostic value in oral cancer, their association has yet to be uncovered." (PMID 34885003, 2021). "Instead, Akt pathway activation in MRE11 overexpressing oral cancer was mediated by the C-X-C chemokine receptor type 4 (CXCR4), suggesting CXCR4 inhibitors as a potential treatment option specifically for this tumor entity." (PMID 34638302, 2021). "A positive correlation between the expression of RUNX2 and CXCR4, as determined by immunohistochemistry analysis, was observed in oral cancer tissues." (PMID 33927349, 2021). "CXCR-4 is a chemokine receptor that regulates chemotaxis, proliferation and invasion of oral cancer cells." (PMID 34885003, 2021). "Several studies have reported the upregulation of CXCR-4 in oral cancer cells when compared with normal epithelium." (PMID 34885003, 2021). "MRE11 and CXCR4 were positively correlated in primary oral cancer tissues and CXCR4 was more highly expressed in oral cancer tissues with lymph node metastasis." (PMID 33927349, 2021). "In parallel with these results, we confirmed an increased expression of CXCR-4 in primary oral cancer patient tumors with LN metastases." (PMID 33854604, 2021). "In this study, the co-localization of CXCR-4/CD133 and CXCR-4/PKC-δ was found in oral carcinoma tissues and cell lines." (PMID 34885003, 2021). "The activation of the SDF-1/CXCR-4 pathway is crucial for the invasion and metastasis of oral cancer cells." (PMID 34885003, 2021). "The staining of CXCR-4 was intense and predominantly found in the cytoplasm of oral carcinoma cells." (PMID 34885003, 2021). "Herein we report the crucial role of MRE11 in oral cancer progression in a nuclease-independent manner and delineate its key downstream effectors including CXCR4." (PMID 33927349, 2021). "CXCR4 knockdown also reversed AKT phosphorylation in oral cancer cells induced by MRE11 overexpression." (PMID 33927349, 2021). "Previous studies have reported that CXCR4 signaling is involved in the establishment of lymph node metastasis in oral cancer through AKT activation." (PMID 33927349, 2021). "To explore potential treatment strategies for MRE11-overexpressing oral cancers in vivo, we tested the efficacy of targeting CXCR4 with neutralizing antibody in mice." (PMID 33927349, 2021). "Further western blotting analysis confirmed that CXCR4 expression in oral cancer cells was decreased when MRE11 was knockdowned." (PMID 33927349, 2021). "This is the first study to highlight the significance of MRE11 in oral cancer progression, and adds to the growing body of literature indicating the importance of the chemokine receptor CXCR4 in a multitude of cancers." (PMID 33927349, 2021). "We also studied their correlation with clinicopathological factors and the possibility of using CXCR-4/CD133 as well as CXCR-4/PKC-δ double positivity to predict poor prognosis in oral cancer." (PMID 34885003, 2021).
oral cancer (continued). "For example, molecular targeting of C-X-C motif chemokine receptor 4 (CXCR4) on vascular endothelial cells induced tumor angiogenic inhibition triggered necrosis (TAITN) in oral cancer, although HIF-1α was induced in the hypoxic and the necrotic tumor tissue." (PMID 31533245, 2019). "Perhaps of high relevance to this review, bacterial products have been reported to increase the expression of CXCR4 on oral cancer cells." (PMID 25999952, 2015). "The CXCL12-CXCR4 biological axis consisting of the chemotactic factor CXCL12 and its specific receptor CXCR4 plays an important role in oral cancer metastasis." (PMID 25866764, 2015). "We previously demonstrated that B88 cells, which are oral cancer cells that express the chemokine receptor CXCR4, specifically metastasize to cervical lymph nodes via a stromal cell-derived factor (SDF)-1 gradient produced by the lymphatic stroma." (PMID 25536052, 2014). "In this study, we examined the metastasis-related miRNAs induced by the SDF-1/CXCR4 system using B88-SDF-1 oral cancer cells, which exhibit functional CXCR4 and distant metastatic potential in vivo." (PMID 25536052, 2014). "We have previously demonstrated that a stromal cell-derived factor-1 (SDF-1; CXCL12)/CXCR4 system is involved in the establishment of metastasis in oral cancer." (PMID 25536052, 2014). "We further examined miR-518c-5p expression using an oral cancer cell line, HNt, in which the expression of CXCR4 was 7.5-fold lower than that in B88 cells." (PMID 25536052, 2014). "We investigated miRNA downstream of the SDF-1/CXCR4 system using the oral cancer cell line, B88-SDF-1, which have an autocrine SDF-1/CXCR4 system and exhibit distant metastatic potential in vivo." (PMID 25536052, 2014). "We investigated novel therapeutic downstream target(s) of the SDF-1/CXCR4 system using the oral cancer cells, B88-SDF-1, which have an autocrine SDF-1/CXCR4 system and exhibit distant metastatic potentials in vivo." (PMID 24236200, 2013). "A recent immunohistochemical study has confirmed that this relationship showing a significant relationship between CXCL12 and CXCR4 was found both in potentially malignant lesions and oral cancer." (PMID 24376459, 2013). "To date, CXCR4 has been demonstrated to be overexpressed in more than 23 human cancers, including breast cancer, ovarian cancer, and oral cancer." (PMID 22496601, 2012). "In the present study, we demonstrated the novel transcriptional regulation of CXCR4 via the transcription factor KLF2 in vesnarinone-treated oral cancer cells." (PMID 19671192, 2009). "Our results indicated that vesnarinone downregulates CXCR4 expression via the upregulation of KLF2 in oral cancer." (PMID 19671192, 2009). "Downregulation of CXCR4 mRNA by treatment with vesnarinone was also detected in oral cancer cells, ACC-M, in a time dependent manner." (PMID 19671192, 2009). "In addition, miR-518c-5p has been suggested to participate in the growth and metastasis of oral cancer by targeting the SDF-1/CXCR4 system." (PMID 37981573, 2023). "Moreover, AKT is partially modulated by SDF1/CXCR4 interactions, and α-hederin has shown reductive capabilities for oral cancer SCC-25 cell lines." (PMID 36986504, 2023). "We speculated that the early dissemination and metastasis of OSCC may be related to the driving mutations such as SMARCA4, CXCR4 and RUNX3, which provides a theoretical basis for the future study on the mechanism of early spread and metastasis of oral cancer." (PMID 36424557, 2022). "We speculated that there may be an interaction between pDC infiltration and CXCR-4 expression in the oral cancer microenvironment." (PMID 33854604, 2021). "The CXCR-4 signaling pathway regulates migration and metastasis of oral cancer cells." (PMID 34885003, 2021). "Moreover, CXCR-4 stably transfected in oral cancer cells frequently induces metastasis to cervical LN in nude mice." (PMID 33854604, 2021).
oral cancer (continued). "To further support our hypothesis, we showed that direct TNF-α stimulation upregulates CXCR-4 expression in an oral cancer Cal 27 cell line via NF-κB activation, and addition of TNF-α neutralizing antibodies could decrease the pDC-CM-mediated NF-κB activation." (PMID 33854604, 2021). "In addition to oral cancer tissues, CXCR-4 expression has also been identified in oral precancerous lesions." (PMID 34885003, 2021). "Notably, the CXCR-4-positive cells were found to express CD133 in human oral cancer tissues and cell lines." (PMID 34885003, 2021). "Interestingly, TGF-β1-induced EMT of oral carcinoma cells has found to be accompanied by an increase in CXCR-4 expression." (PMID 34885003, 2021). "CXCR4 was previously found to be involved in the production of pro-inflammatory cytokines, such as interleukin 6 (IL-6), which is increased after CXCR4 activation in microglia, human oral cancer cells, and fibroblasts." (PMID 27716214, 2016). "SDF-1/CXCR4-driven invasion of oral cancer is reported to be dependent upon NFkB signaling." (PMID 25999952, 2015). "We have demonstrated that blocking CXCR4 may be a potent anti-metastatic therapy for CXCR4-related oral cancer." (PMID 24236200, 2013). "The findings of the present study suggest that vesnarinone might be useful as an anti-metastatic agent for patients with CXCR4-related oral cancer." (PMID 19671192, 2009). "Thus, in this study, we examined the transcriptional regulation of CXCR4 by chemotherapeutic agents in an oral cancer cell line, B88, which expresses high levels of CXCR4, and which exhibits lymph node metastatic potential in vivo." (PMID 19671192, 2009). "It is consistent with the study on oral carcinomas which showed that CXCR4 could influence EMT formation and cancer invasion." (PMID 19002187, 2008). "However, the miRNAs that contribute to metastases induced by the SDF-1/CXCR4 system in oral cancer are largely unknown." (PMID 25536052, 2014). "If further molecular mechanism of mGluR5 against cancer metastasis could be clarified, blocking mGluR5 with antagonists such as MPEP and MTEP could prevent metastasis in CXCR4-related oral cancer without causing side effects." (PMID 24236200, 2013). "Notably, blockage of CXCR4 as well as its ligands CXCL12 during oral cancer promotion could be employed as a new therapeutic strategy in future." (PMID 22496601, 2012). "On the other hand, the co-localization of CXCR-4 with PKC-δ or CD133 was studied using immunofluorescence in the tissues and cell line of oral cancer." (PMID 34885003, 2021). "CXCR4, a downstream effector of RUNX2 transcription factor, presents an exciting and viable target in oral cancer, with both antagonists and CXCR4 directed imaging in the mature stage of development." (PMID 33927349, 2021). "Taken together, the aim of our study is to investigate the expression pattern of CXCR-4, PKC-δ and CD133 in oral cancer tissues and cell line." (PMID 34885003, 2021). "Increased expression of CXCR-4, PKC-δ and CD133 indicates their role in the progression of oral cancer." (PMID 34885003, 2021). "CXCR4 antagonist, AMD3100, decreases cell migration and cell invasion of oral cancers and inhibits lymph node metastasis in these cells due to the reduced migration of tumor cells by the suppression of the SDF-1/CXCR4 gradient and inhibition of lymphangiogenesis." (PMID 39001265, 2024). "CXCR-4, PKC-δ, and CD133, in particular, may control the aggressive phenotype and invasion of oral cancer cells." (PMID 34885003, 2021). "Despite several studies, the co-expression of CXCR-4 and CD133 and its significance is still largely unknown in oral cancer." (PMID 34885003, 2021). "Therefore, we aimed to investigate the impact of CXCR-4 and CD133 double positivity in the prognosis of oral cancer." (PMID 34885003, 2021). "Moreover, CXCR-4/CD133, CXCR-4/PKC-δ and CD133/PKC-δ double positivity were highly correlated with worse survival in oral cancer as calculated by Kaplan–Meier analysis." (PMID 34885003, 2021).